XIST (X inactive specific transcript)
Diseases named in the same sentence as XIST in open-access papers (continued):
Sharing a sentence is not in itself a finding about the gene and the disease.
glioma (continued). "The ceRNA regulatory network, in which XIST can compete for endogenous miRNAs was confirmed in nasopharyngeal carcinoma, esophageal squamous cell carcinoma, gastric cancer, pancreatic cancer, prostate cancer, hepatocellular carcinoma, glioma, bladder cancer." (PMID 29752340, 2018). "One recent study pointed out a novel role of XIST in regulating a glioma microenvironment." (PMID 30116729, 2018). "Consistently, other miRNAs, such as miR-92b and miR-210, may also regulate the expression of XIST in gliomas." (PMID 28293170, 2017). "The western blot analysis also revealed a decrease in CXCR7 expression in the XIST(−) group, which may explain the way in which XIST knockdown impaired glioma angiogenesis." (PMID 28287613, 2017). "Then, XIST knockdown was conducted to investigate its role in glioma chemoresistance to TMZ." (PMID 28831025, 2017). "The cell proliferation of U251/TMZ and LN229/TMZ cells was significantly suppressed by XIST knockdown, whereas promoted by miR-29c inhibition; the suppressive effect of XIST knockdown on glioma cell proliferation coule be partially reversed by miR-29c inhibition." (PMID 28831025, 2017). "In view of the key role of miR-29c in cancers, in particular the chemosensitivity of cancer cells; we further investigated whether XIST regulates the chemoresistance of glioma cell to TMZ through miR-29c." (PMID 28831025, 2017). "Here, we investigated whether the MMR pathway were involved in XIST/miR-29c regulation of glioma cell chemoresistance to TMZ by measuring the protein levels of MSH6, MGMT, and SP1." (PMID 28831025, 2017). "XIST can inhibit miR-29c expression by directly targetting TMZ-resistant glioma cells." (PMID 28831025, 2017). "Altogether, further studies should focus on the XIST-miRNA axis in glioma research and treatment." (PMID 28293170, 2017). "Furthermore, we also assessed the combined effect of XIST and miR-29c on glioma cell proliferation and chemoresistance to TMZ." (PMID 28831025, 2017). "Whether vascular endothelial growth factor A or other mediators of angiogenesis are involved in XIST-regulated glioma angiogenesis also deserves further investigation." (PMID 28287613, 2017). "However, the mechanism by which XIST affects the chemoresistance of glioma cells remains to be investigated." (PMID 28831025, 2017). "However, the mechanism by which XIST regulates the chemoresistance of glioma cells to TMZ remains to be investigated." (PMID 28831025, 2017). "Whether XIST can interact with miR-29c to affect glioma cell proliferation and its chemoresistance to TMZ remain to be uncovered." (PMID 28831025, 2017). "Similarly, XIST regulates miR-429, thus promoting tumorigenicity and angiogenesis in gliomas." (PMID 33980320, 2021). "Moreover, miR-204-5p has been identified as another target of XIST in glioma cells." (PMID 34179019, 2021). "Moreover, XIST expression levels are increased in glioma and human glioma stem cells." (PMID 33980320, 2021). "Moreover, XIST knockdown can sensitize TMZ-resistant glioma cells to TMZ." (PMID 28831025, 2017). "Moreover, the effect of XIST knockdown on glioma cell chemoresistance could be partially reversed by miR-29c inhibition." (PMID 28831025, 2017). "Furthermore, 24 h after transfection, cells were treated with a series dose of TMZ (7.5, 15, 30, 60, 120, 240, and 480 μM) for 24 h; the cell viability was then determined using MTT assays to assess the combined effect of XIST and miR-29c on glioma cell chemoresistance to TMZ." (PMID 28831025, 2017). "XIST/miR-29c may be a potential therapeutic target for glioma treatment." (PMID 28831025, 2017). "We then investigated whether XIST affects the chemoresistance of glioma cells to TMZ." (PMID 28831025, 2017). "Knockdown of XIST upregulates miR-137, enhancing BTB permeability and decreasing angiogenesis in glioma via inhibition of the transcription factors forkhead box C1 (FOXC1) and ZO-2." (PMID 33980320, 2021).
glioma (continued). "Of note, XIST showed lower expression levels in DA tumors (versus some AA and GBM), while FSTL5 and SFRP2 expression was greater in DA vs AA gliomas." (PMID 32647207, 2020). "Multiple lncRNAs have been reported to be involved in the initiation and progression of glioma, which include CRNDE, H19 and XIST, GAS, Malat1, Hotair, and SOX2ot." (PMID 31052326, 2019). "In contrast to XIST, miR-137 was downregulated in GECs, and miR-137 overexpression contributed to the increase in BTB permeability and inhibition of glioma angiogenesis by attenuating FOXC1 and ZO-2 expression." (PMID 28287613, 2017). "Stable XIST-silenced GECs were transfected with antagomir-137 to investigate the effects of miR-137 on XIST-regulated BTB permeability and glioma angiogenesis." (PMID 28287613, 2017). "The present study investigated the expression of XIST, miR-137 and FOXC1 in GECs, and their role in BTB permeability and glioma angiogenesis." (PMID 28287613, 2017). "To verify the role of XIST in BTB permeability and glioma angiogenesis, we first evaluated the expression of XIST in GECs and ECs." (PMID 28287613, 2017). "In the present study, we monitored the protein levels of MSH6, MGMT, and SP1 in response to cotransfecting XIST and miR-29c in TMZ-resistant glioma cell lines." (PMID 28831025, 2017). "In the present study, we show that XIST/miR-29c coregulates SP1 and MGMT expression in TMZ-resistant glioma cell lines." (PMID 28831025, 2017). "XIST knockdown increased BTB permeability and inhibited glioma angiogenesis by inhibiting FOXC1 and ZO-2 expression through upregulation of miR-137." (PMID 28287613, 2017). "For instance, in glioma models, ASO-mediated knockdown of XIST could theoretically restore miR-29c activity, thereby decreasing SP1 and MGMT expression, two key mediators of chemoresistance." (PMID 41601966, 2026). "However, the expression of the lincRNAs XIST, MALAT1 and H19, which are m6 A-modified transcripts, increased in glioma stem cells." (PMID 40382536, 2025). "Moreover, the XIST/miR-133a/SOX4 axis also promotes cell growth, metastasis, and the epithelial-mesenchymal transition (EMT), providing a novel target for glioma treatment." (PMID 34930117, 2021). "Moreover, it has been also shown that XIST is involved in the blood–tumor barrier (BTB) permeability and glioma angiogenesis." (PMID 32977537, 2020). "XIST/miR-29c correlation has been revealed to regulate DNA repair protein MGMT and transcription factor specificity protein 1 (SP1), participating in conferring TMZ resistance of gliomas." (PMID 32977537, 2020). "XIST was found to be overrepresented in glioma endothelial cells (GECs), and XIST knockdown increased permeability of the brain-tumor barrier (BTB) and inhibited glioma angiogenesis, which may have beneficial effects on GBM treatment." (PMID 30116729, 2018). "In view of the important role of miR-29c in regulating cancer cell growth and invasion, as well as glioma chemoresistance to TMZ, we validated whether XIST affects the chemoresistance of glioma cells to TMZ through miR-29c." (PMID 28831025, 2017). "The results showed that glioma cell viability was repressed by TMZ treatment in a dose-dependent manner; TMZ-induced repression of glioma cell viability could be amplified by XIST knockdown." (PMID 28831025, 2017). "XIST inhibition increased BTB permeability and suppressed glioma angiogenesis." (PMID 28287613, 2017). "In this regard, recent studies have demonstrated that lncRNAs in gliomas can serve as molecular decoys, which move proteins or RNAs away from a specific location, like a “sponge” to miRNAs (e.g., HOTAIR/miR-326, CASC2/miR-21, XIST/miR-152, and Gas5/miR-222)." (PMID 28293170, 2017). "Taken together, these data suggest that XIST can inhibit miR-29c expression by directly binding to miR-29c and subsequently up-regulate the expression of SP1 and MGMT to promote the chemoresistance of glioma cells to TMZ." (PMID 28831025, 2017).
glioma (continued). "XIST knockdown significantly suppressed glioma cell proliferation in the presence or absence of TMZ treatment." (PMID 28831025, 2017). "XIST knockdown increased BTB permeability and inhibited glioma angiogenesis." (PMID 28287613, 2017). "Overall, the present study demonstrates that XIST plays a pivotal role in BTB permeability and glioma angiogenesis, and the inhibition of XIST may be a potential target for the clinical management of glioma." (PMID 28287613, 2017). "Thus, we hypothesized that XIST regulates BTB permeability and glioma angiogenesis by sponging miR-137." (PMID 28287613, 2017).
non-small cell lung carcinoma (41 papers, 2015 to 2025). A group of at least three distinct histological types of lung cancer, including non-small cell squamous cell carcinoma, adenocarcinoma, and large cell carcinoma. "XIST was associated with chemotherapy resistance in non-small cell lung cancer (NSCLC), and it also can expedite the progression of LUAD." (PMID 33771173, 2021). "An oncogenic role of XIST mediated by its ceRNA activity has also been consistently indicated by different studies of non-small-cell lung cancer (NSCLC)." (PMID 35054794, 2022). "The lncRNA XIST is closely related to non-small cell lung cancer and can promote cancer cell proliferation, invasion, and metastasis." (PMID 36457751, 2022). "LncRNA XIST has been shown to be abnormally expressed in various tumor tissues including hepatocellular carcinoma, non-small cell lung cancer and malignant glioma." (PMID 33858324, 2021). "Studies have found that lncRNA XIST is abnormally expressed in multiple tumor tissues including non-small-cell lung cancer, glioblastoma, gastric cancer, hepatocellular carcinoma, ovarian cancer, and breast cancer." (PMID 33858324, 2021). "Down-regulation of XIST has been reported to reduce chemoresistance in non-small cell lung cancer cells by inhibiting autophagy." (PMID 33228517, 2020). "lncRNA XIST was found to promote EMT through the regulation of ZEB2 by acting as a miRNA-367/141 ceRNA in non-small cell lung cancer." (PMID 33287341, 2020). "In non-small-cell lung cancer, XIST has been reported to regulate the cell proliferation and apoptosis by modulating the MAP3K3 pathway, and the MAPK pathway was associated with the PD pathogenesis." (PMID 30867898, 2019). "Long non-coding RNAs are known to often contribute to unrestricted growth and invasion of cancer cells, with XIST shown to be up-regulated in several cancers, including colorectal, gastric, non-small cell lung cancer (NSCLC)." (PMID 30866571, 2019). "XIST has been shown to be oncogenic in non-small cell lung cancer, where it increases Bcl-2 levels by functioning like a sponge for miR-449a, which then down-regulates Bcl-2." (PMID 30555629, 2018). "XIST acts as an oncogene in non-small cell lung cancer by epigenetically repressing KLF2 expression." (PMID 29371940, 2017). "Further investigation revealed that XIST acts as an oncogene in non-small cell lung cancer by epigenetically repressing KLF2 expression." (PMID 27911852, 2017). "The study suggests that lncRNA XIST may facilitate TGF-beta-induced EMT in non-small cell lung cancer through the modulation of the miR-367/141-ZEB2 signaling mechanism." (PMID 37915049, 2023). "Also, it is revealed that the down-regulation of XIST can inhibit the development of non-small cell lung cancer." (PMID 35581633, 2022). "The expression of lncRNA XIST is increased in non-small cell lung cancer." (PMID 36035993, 2022). "Recent studies have shown that XIST may suppress the development of non-small cell lung cancer by activating the miR-335/SOD2/ROS signaling pathway." (PMID 34804157, 2021). "Moreover, XIST mediated oncogenic effects is partially through its epigenetically silencing of KLF2 expression in non-small cell lung cancer." (PMID 29568404, 2018). "For example, the fifth ranked regulator MYC was recently proved to mitigate its oncogenic activity by chaperone-mediated autophagy (CMA) regulation and the ninth ranked regulator XIST was determined to increase autophagy activity in non-small-cell lung cancer by regulation of ATG7." (PMID 30400235, 2018). "Previous studies found that lncRNA XIST was upregulated in non small cell lung cancer (NSCLC) and could promote cancer cell proliferation and invasion." (PMID 28938648, 2017). "In non-small cell lung cancer (NSCLC), XIST acts as the ceRNA of miR-744, inhibits the feedback loop of miR-744/RING1 and activates the Wnt/ β-catenin signaling pathway, which results in enhanced proliferation of NSCLC cells." (PMID 39030557, 2024).
non-small cell lung carcinoma (continued). "The lncRNA XIST can regulate X chromosome silent transcription and act as an miRNA sponge upregulating SOD2 to inhibit the development of non-small cell lung cancer." (PMID 34079798, 2021). "Emerging evidence indicates that the lncRNA X inactive-specific transcript (XIST) is dysregulated in several tumor types, including non-small cell lung cancer (NSCLC)." (PMID 32209729, 2020). "A research showed XIST and HIF1A-AS1 lncRNA were detectable in tumor tissues and serum in NSCLC (non-small cell lung cancer) patients." (PMID 31619233, 2019). "Serum lncRNAs, SPRY4-IT1, ANRIL, NEAT1, XIST and HIF1A-AS1 were identified as the potential predictor for the tumorigenesis of non-small-cell lung cancer." (PMID 26674525, 2015).
gastric cancer (37 papers, 2014 to 2025). A primary or metastatic malignant neoplasm involving the stomach. "In gastric cancer, the lncRNA XIST, when overexpressed, adsorbed miR-132 and caused upregulation of PXN in cancer cells." (PMID 34946859, 2021). "In gastric cancer, overexpression of XIST was significantly associated with larger tumor size, distant metastasis, lymph node invasion, and TNM stage of patients." (PMID 32489472, 2020). "Univariate analysis demonstrated that distant metastasis (P = 0.018), TNM stage (P = 0.027) and XIST expression level (P = 0.002) were significantly associated with overall survival of gastric cancer patients." (PMID 27620004, 2016). "Overexpression of lncRNA XIST was closely associated with an aggressive tumor phenotype and adverse prognosis in gastric cancer patients." (PMID 27620004, 2016). "Collectively, these results suggest that NAT10 promotes VEGFA expression and angiogenesis in gastric cancer by acetylating the lncRNA XIST." (PMID 40860183, 2025). "The lncRNA XIST is oncogenic in colorectal, bladder, and gastric cancers and plays a tumor-suppressor role in breast and prostate cancers." (PMID 39802612, 2025). "In gastric cancer, XIST lncRNA-expression levels were found to be overexpressed in both GC patients and cell lines, and its upregulation was linked to tumor size, positive lymph nodes, and the TNM stage." (PMID 38542354, 2024). "Some typical "microRNA sponges" such as H19 30, PRKCA-AS1 31, HOTAIR 32 and XIST 33 have been involved in regulating tumor progression in nasopharyngeal carcinoma, uveal melanoma and gastric cancer." (PMID 38370382, 2024). "Another interesting lncRNA is the X-inactive specific transcript (XIST) that has been described to be overexpressed in various cancers, including gastric cancer." (PMID 38542354, 2024). "Silencing lncRNA XIST can also promote gastric cancer cell apoptosis through the lncRNA XIST/miR-132/paxillin signaling axis." (PMID 37175948, 2023). "Several of the induced lncRNAs, such as MALAT1, PVT1, and XIST, have also been shown to have specific properties in gastric cancer and were also identified as upregulated in NPC (25, –, 27)." (PMID 35435703, 2022). "For example, downregulation of has-let-7b-5p enhances XIST expression leading to cisplatin resistance in gastric cancer." (PMID 36506097, 2022). "For instance, XIST functioned as a molecular sponge to repress the function of miR-101 in gastric cancer." (PMID 33542956, 2021). "In a survey, the relationship between lncRNA XIST expression and clinicopathological characteristics was investigated in gastric cancer patients and lncRNA XIST was markedly overexpressed in gastric cancer tissues." (PMID 34337048, 2021). "For instance, lncRNA XIST contributes to gastric cancer via cooperating with the miR-185/TGF-β1 axis." (PMID 34176471, 2021). "XIST can influence gastric cancer cell proliferation, migration, intrusion, and tumor growth by sponging miR-101." (PMID 33364236, 2020). "The results of the forest plot demonstrated that gastric cancer, pancreatic cancer or osteosarcoma patients with higher expression of XIST in the tumor tissues were more prone to DM." (PMID 29568404, 2018). "Another study has revealed that XIST promotes gastric cancer proliferation and invasion through sponging miR-497." (PMID 29559853, 2018). "In gastric cancer, XIST affects the cell proliferation, migration and invasion, as well as tumor growth through sponging miR-101." (PMID 30463570, 2018). "XIST is associated with tumor progression through targeting miR-34a-5p or miR-497/MACC1 axis in nasopharyngeal carcinoma and gastric cancer individually." (PMID 29568404, 2018). "The results of the forest plot demonstrated that gastric cancer, pancreatic cancer or cervical squamous cell carcinoma patients with higher expression of XIST in the tumor tissues, were more liable to developing LNM." (PMID 29568404, 2018).